HTRA1 (HtrA serine peptidase 1)
Diseases named in the same sentence as HTRA1 in open-access papers (continued):
Sharing a sentence is not in itself a finding about the gene and the disease.
osteoarthritis (16 papers, 2013 to 2024). A noninflammatory degenerative joint disease occurring chiefly in older persons, characterized by degeneration of the articular cartilage, hypertrophy of bone at the margins and changes in the synovial membrane. "Concerning the serine protease HtrA1, another undesirable marker which was over-expressed in osteoarthritis and associated with chondrocyte dedifferentiation, interestingly, we unambiguously and originally demonstrated that BMP-2 induces its down-regulation." (PMID 28837082, 2017). "However, human HTRA1 has been linked with the pathogenesis of several abnormalities, such as osteoarthritis, rheumatoid arthritis, and even cancers." (PMID 28251419, 2017). "Notwithstanding, the herein described potent and selective CKP inhibitors, which also inhibit mouse HTRA1, may serve as valuable tools to further investigate HTRA1 biology and could have other pharmacological applications in HTRA1-associated diseases, such as osteoarthritis and osteoporosis." (PMID 38777835, 2024). "This review examines the role of HTRA1 in bone biology, osteoarthritis, intervertebral disc (IVD) degeneration and tumorigenesis." (PMID 31867863, 2020). "HtrA1 has been shown to be involved in physiological and pathological processes such as osteoarthritis, preeclampsia, and leukoencephalopathy (6, –8)." (PMID 30484491, 2018). "Later, it was shown that human HtrA1 was significantly elevated in the cartilage of osteoarthritis patients." (PMID 30484491, 2018). "HtrA1 was also suggested to stimulate progression of arthritis through degrading cartilage matrix in osteoarthritis." (PMID 29695130, 2018). "High temperature requirement A1 (HTRA1), a serine protease, is strongly expressed in the presence of stressors in murine osteoarthritis models." (PMID 27478294, 2016). "Furthermore, mouse tissues afflicted with late-stage osteoarthritis after destabilization surgery expressed HTRA1, which diminished the expression of transforming growth factor beta 1 (TGF-β1)." (PMID 38927030, 2024). "Interestingly, in osteoarthritis, a multifactorial joint inflammatory disorder, the levels of HTRA1 mRNA were 7-fold elevated in the cartilage of early-stage osteoarthritis patients compared to healthy controls." (PMID 38927030, 2024). "HTRA1 expression is increased in synovial fluid of osteoarthritis patients and may contribute to cartilage degradation." (PMID 36064790, 2022). "HtrA1, Ddr-2, and Mmp-13 are reliable biomarkers for osteoarthritis (OA), yet the exact mechanism for the upregulation of HtrA-1 is unknown." (PMID 23755017, 2013).
ovarian carcinoma (16 papers, 2010 to 2024). A malignant neoplasm originating from the surface ovarian epithelium. "Although it is currently recognized that HTRA1 expression is reduced in different types of ovarian carcinoma, in high-grade serous OC, nuclear expression of cleaved HtrA1 is associated with good prognosis." (PMID 34563186, 2021). "Numerous studies have linked HTRA1 to tumorigenesis since it has been found to be down-regulated in many tumors including prostate cancer, ovarian cancer, and melanoma." (PMID 29269789, 2017). "Although the prognostic effect of HtrA1 in ovarian carcinoma is unknown, HtrA1 downregulation has been reported in association with resistance to cisplatin." (PMID 30131069, 2018). "The down-regulation of HTRA1 was associated with ovarian cancer metastasis." (PMID 20969748, 2010). "Hence, together with our data obtained in the validation set, these data may support previous results in gastric and ovarian cancer which have linked HTRA1 proficiency to better therapeutic responsiveness indicating that HTRA1 is a predictive marker." (PMID 23580433, 2013). "Another study reports that an overexpression of HtrA1 in ovarian cancer cells inhibits epidermal growth factor receptor (EGFR) activation, leading to lower levels of AKT/MAPK phosphorylation and a significant rise in cell death." (PMID 34639128, 2021). "The expression of high temperature requirement factor A1 (Htra1) has been reported to be decreased in ovarian carcinoma, but its prognostic effect remains undetermined." (PMID 30131069, 2018). "In human ovarian cancer tissues, the expression levels of HtrA1 mRNA and protein are significantly lower than in normal epithelial tissues." (PMID 30131069, 2018). "Several studies have indicated that the down regulation of HTRA1 plays an important role in malignant progression of ovarian cancers and melanoma." (PMID 27009842, 2016). "Down-regulation of HtrA1 expression in the ovarian cancer cell line SKOV3 promoted cell anchorage-independent growth, while over-expression of HtrA1 in another ovarian cancer cell line OV2O2 induced cell death." (PMID 22761798, 2012). "The results revealed that HtrA1 mRNA expression in ovarian cancer was significantly decreased compared with normal ovarian tissue." (PMID 22935172, 2012). "Second, HtrA1 expression in human ovarian cancers was significantly decreased compared with normal ovary or with benign ovarian neoplasms." (PMID 22761798, 2012). "The majority of cancer-related HTRA1 research hypothesized it as a tumor suppressor, such as, ovarian cancer, endometrial cancer, hepatocellular carcinoma, and melanoma." (PMID 38287020, 2024). "Furthermore, correlation of HTRA1 mRNA and protein expression has been reported for a number of cancers such as endometrial and ovarian cancer as well as for melanoma cell lines, suggesting equal relevance of mRNA compared to protein measurement." (PMID 23580433, 2013). "HtrA1 is considered to be a tumor suppressor gene that reduces the transforming ability of fibroblasts and suppresses the growth of highly invasive tumors, such as ovarian cancer and invasive melanoma." (PMID 22935172, 2012). "Additionally, the degradation of the X-linked inhibitor of apoptosis protein (XIAP) by HtrA1 plays a role in the cellular response to chemotherapy, suggesting that restoring HtrA1 expression could be a promising therapeutic approach for treating ovarian cancer." (PMID 38793064, 2024). "Moreover, in vitro studies show that HtrA1 disrupts the microtubule networks by directly targeting tubulins for degradation; in ovarian cancer cells, HTRA1 knockdown enhances cell migration, whereas HTRA1 overexpression attenuates it, suggesting that HtrA1 may regulate cancer metastasis." (PMID 34639128, 2021).
melanoma (15 papers, 2006 to 2024). A malignant, usually aggressive tumor composed of atypical, neoplastic melanocytes. "In particular, HTRA1 downregulation has been previously shown to be associated with the metastatic phenotype of melanoma cells, while HTRA1 expression suppressed growth and matrix invasion of metastatic cells." (PMID 23580433, 2013). "HTRA1 is involved in several vascular diseases and its altered expression has been reported for a few cancers such as ovarian, lung cancer, and melanoma, where a tumor suppressor role was proposed." (PMID 37834386, 2023). "HtrA1 is suggested to function as a tumour suppressor to promote cell death; studies with metastatic melanoma cells show that an overexpression of HtrA1 inhibits cell proliferation in vitro and prevents tumour outgrowth in vivo." (PMID 34639128, 2021). "HTRA1 expression is decreased in some cancers, such as melanomas and lung and ovarian cancer, and the reduction of cell proliferation after an increase of its expression suggests a tumor suppressor role for this protein." (PMID 27809811, 2016). "This was the first study reporting clinical data of patients with malignant melanoma and demonstrated higher HtrA1 levels in primary tumors compared with metastases." (PMID 26035313, 2015). "A similar down-regulation of HtrA1 was observed in melanomas, and over-expression of HtrA1 inhibited cell proliferation in vivo in a mouse model." (PMID 22761798, 2012). "Fifth, overexpression of HtrA1 in a metastasis-competent melanoma cell line strongly inhibited proliferation and invasive capability, and reduced HtrA1 expression was related to progression of melanomas in patient samples." (PMID 22761798, 2012). "Furthermore, it has been reported that the expression of HtrA1 is down-regulated in the progression and invasion of ovarian cancer, melanoma, lung cancer, and mesothelioma." (PMID 30484491, 2018). "The first clinical study was carried out on melanoma by Baldi and colleagues, who found significant HtrA1 upregulation in the primary tumor compared with metastases, and suggested that HtrA1 expression could be an indicator of disease progression." (PMID 26035313, 2015). "Because an even greater HTRA1 downregulation in lymph node metastases compared to the primary sites was evident in lung cancer and malignant melanoma, this strongly points to a particular benefit for node-positive patients to have high expression of the tumor suppressor HTRA1." (PMID 23580433, 2013). "The first clinical study on melanoma was carried out by Baldi and colleagues, who reported significant HtrA1 upregulation in primary tumours compared with that in metastases, and suggested that HtrA1 expression could be an indicator of disease progression." (PMID 38609535, 2024). "HtrA1 has been reported to be absent or substantially down-regulated in a variety of cancers during their progression, including gastric, breast, ovarian, endometrial and hepatocellular carcinomas, as well as mesothelioma and melanoma." (PMID 22761798, 2012).
preeclampsia (15 papers, 2012 to 2025). Preeclampsia is a hypertensive disorder of pregnancy that is characterized by new-onset hypertension with proteinuria presenting after 20 weeks of gestation, and depending on mild or severe forms may initially present with severe headache, visual disturbances, and hyperreflexia. "Several studies have reported an association between HtrA1 dysregulation and preeclampsia, especially the early-onset subtype which occurs before 34 weeks of gestation and usually presents with more severe forms of the disease." (PMID 34639128, 2021). "Disturbances in Htra1 regulation and function are implicated in vascular diseases, preeclampsia, and FGR27,28,41,58,59." (PMID 32884071, 2020). "Given the association between dysregulation in placental Htra1 in preeclampsia and FGR27,28, such studies are warranted." (PMID 32884071, 2020). "Moreover, disturbances in Htra1 regulation and function are implicated in preeclampsia, and FGR32,42–45." (PMID 36042379, 2022). "Thus, HTRA-1 may underlie ROP protection in preeclampsia and represent an avenue for disease prevention, which does not currently exist." (PMID 33281553, 2020). "For example, a significant increase in HTRA1 plasma levels were found in pregnant women during 28–32 gestational weeks in cases of preeclampsia and preeclampsia- intrauterine growth restriction compared with the control group." (PMID 40427411, 2025). "The aim of this study was to evaluate the functional role of HTRA1 in in vitro models of human placenta in order to define the role of this serine protease in preeclampsia (PE)." (PMID 37232715, 2023). "In fact, HTRA1 expression increases from the first to the third trimester of normal pregnancy, and altered HTRA1 expression was found in placentas from gestational trophoblastic diseases and preeclampsia (PE)." (PMID 37232715, 2023). "The aim of this study was to evaluate the functional role of HTRA1 in in vitro models of human placenta in order to investigate the possible role of this serine protease in preeclampsia." (PMID 37232715, 2023). "Placental HTRA1 expression is upregulated in the third trimester when early-onset preeclampsia manifests, and HtrA1 serum levels are likewise elevated, making it a potential diagnostic marker." (PMID 34639128, 2021). "Certainly, if decreased HTRA-1 is a function of preeclampsia, and somehow conferred to the infant resulting in ROP protection, we would expect this difference to be present at birth." (PMID 33281553, 2020). "Our results show a novel phenomenon present in P. gingivalis-induced FGR, with relevance to human disease since dysregulation of placental Htra1 and placental oxidative stress are features of preeclamptic placentas and preeclampsia with FGR." (PMID 32884071, 2020). "In humans high concentrations of the HTRA1 protein in the placenta and serum of preeclampsia patients have been reported." (PMID 33352987, 2020). "Future work will be directed at understanding mechanisms of HTRA-1 regulation both within the context of preeclampsia and in the neurosensory retina and developing retinal vasculature, allowing for targeted interventions." (PMID 33281553, 2020). "Specifically, we found that HTRA-1 protein expression was significantly decreased in the systemic circulation of infants born in the setting of preeclampsia when measured in a standardized GA window of 28–33 weeks." (PMID 33281553, 2020). "Taken together, these data suggest it is plausible that HTRA-1 can facilitate both preeclampsia-mediated ROP protection and participate in local neovascular ROP pathophysiology." (PMID 33281553, 2020). "Certainly, there is precedent for systemic dysregulation of HTRA-1 in preeclampsia though the precise changes relative to gestation as well as maternal and infant disease are not well elucidated owing to the paucity of data and variable GA assessments." (PMID 33281553, 2020).
preeclampsia (continued). "Our work identifies a novel role for the serine protease HTRA-1 as a potential mediator of ROP protection in the setting of early-onset preeclampsia and a dose-dependent biomarker for ROP." (PMID 33281553, 2020). "They describe a high amount of the full-length form in healthy human placenta and, in contrast to that, a total down-regulation of the full-length form and an up-regulation of a 30 kDa truncated form of HTRA1 in preeclampsia placenta." (PMID 25329061, 2014). "Thus, our data suggest a role for HTRA-1 in preeclampsia-mediated ROP protection which can be assessed in the systemic circulation." (PMID 33281553, 2020). "This is compelling evidence that HTRA-1 expression may be influenced by preeclampsia and the in utero environment." (PMID 33281553, 2020). "This suggests that maternal preeclampsia may confer lower HTRA-1 expression, which is then protective for infant ROP development." (PMID 33281553, 2020). "Additionally, HTRA1 concentration increases in the maternal plasma of gestations complicated by preeclampsia with intrauterine growth restriction compared with control." (PMID 28251419, 2017). "Furthermore the level of HTRA1 in placenta with preeclampsia (PE) or trophoblastic diseases was reported to be deregulated compared with normal placenta." (PMID 25329061, 2014). "More specifically, we demonstrate that elevated systemic HTRA-1 expression is significantly associated with increased risk of preterm infant ROP and conversely that decreased systemic HTRA-1 expression is significantly associated with preeclampsia within a discovery cohort of maternal/infant pairs." (PMID 33281553, 2020). "Our work describing potential roles for HTRA-1 as a disease biomarker and mediator of ROP protection in preeclampsia is broadly supported in the literature." (PMID 33281553, 2020). "TGFβ-1, VEGF, IGF-1, and HTRA-1 are unique in that they have all been postulated to play a role in ROP and preeclampsia and have a direct and indirect role in angiogenesis." (PMID 33281553, 2020). "It was reported that the plasma concentration of HTRA1 increases in pregnancies complicated by preeclampsia and IUGR, whilst EPAS1 is typed as a biomarker of early preeclampsia detection." (PMID 31280246, 2019). "In this group we have, for example, the HTRA1 and ACVR1 that have been well documented in preeclampsia." (PMID 24219996, 2013). "Both proteases, HTRA1 and HTRA4, are elevated in the placenta of preeclampsia patients." (PMID 34884497, 2021). "IGF-1 and HTRA-1 demonstrated significantly lower levels of systemic expression in women with early-onset preeclampsia vs. women without preeclampsia." (PMID 33281553, 2020). "However, serum HtrA1 is not altered in the first or second trimester prior to the presentation of early-onset preeclampsia, indicating that HtrA1 is not useful for predicting the disease." (PMID 34639128, 2021). "Importantly, animal studies support a role for aberrancy of HtrA-1 expression in preeclampsia demonstrating that murine lack of HtrA-1 expression phenocopies placental insufficiency found in maternal preeclampsia." (PMID 33281553, 2020). "Analysis in a discovery cohort of 40 maternal-infant pairs found that elevated HTRA-1 (high-temperature requirement-A serine peptidase-1) was significantly associated with increased risk of ROP and the absence of preeclampsia, thus fitting a model of preeclampsia-mediated ROP protection." (PMID 33281553, 2020). "Herein we show that HTRA-1, but not TGFβ-1, VEGF, or IGF-1, may mediate ROP protection in the setting of early-onset preeclampsia." (PMID 33281553, 2020).
CADASIL (14 papers, 2013 to 2025). "We compared the clinical features of this case with known phenotypes of CADASIL caused by p.R75P, HTRA1-related CSVD." (PMID 40634305, 2025). "CAA and CADASIL pathogenesis is clearly initiated by the aggregation of misfolded Aβ and Notch3ECD, respectively, but a significant fraction of the pathological events resulting in vessel dysfunction might be promoted by a loss of HTRA1-mediated protein clearing activity." (PMID 39081996, 2023). "In East Asians, cerebral autosomal dominant arteriopathy with subcortical infarcts and leukoencephalopathy (CADASIL) caused by NOTCH3 mutations, CADASIL2 and CARASIL (recessive) caused by HTRA1 mutations, and moyamoya disease (MD) caused by RNF213 mutations, are particularly prevalent." (PMID 36580209, 2023). "High-temperature requirement protein A1 (HTRA1) aggregations and HTRA1 substrates accumulation are the key links for cerebral autosomal dominant arteriopathy with subcortical infarcts and leukoencephalopathy (CADASIL)." (PMID 37239937, 2023).